PCK2 (phosphoenolpyruvate carboxykinase 2, mitochondrial)
Diseases named in the same sentence as PCK2 in open-access papers (continued):
Sharing a sentence is not in itself a finding about the gene and the disease.
tumor (continued). "Recent studies have demonstrated that PCK2 is important in diabetes and obesity development, as well as tumor cell adaptation." (PMID 34970539, 2021). "Previous studies suggested that downregulation of PCK2 reduced mitochondrial OXPHOS, caused OAA accumulation, and promoted glycolysis in tumor cells." (PMID 34970539, 2021). "Still, more research is warranted to understand the role of PCK1 and PCK2 in different tumor entities." (PMID 33540663, 2021). "Over expression of PCK2 slows the growth of tumor repopulating cell (TRC) in vitro and reduces tumorigenesis in vivo." (PMID 32699530, 2020). "This heterogenous pattern precluded a quantitative assessment of PCK2 immunopositivity in tumor tissue versus normal lung." (PMID 32777161, 2020). "PCK2 is a new tumor suppressor in RCC that we discovered, and for the first time revealed its hypermethylation status in RCC." (PMID 33052225, 2020). "When we analyzed the correlation of glycolytic or gluconeogenic enzyme expression with tumor‐related parameters, we found that in LUAD (r = −0.2, P = 0.0014) and in LUSC (r = 0.13, P = 0.03), PCK2 expression significantly decreased with increasing tumor size." (PMID 32777161, 2020). "First, a xenograft tumor model was constructed by subcutaneous injection of CAKI cells with PCK2 overexpressed in the axilla of nude mice." (PMID 33052225, 2020). "The results showed that the levels of endoplasmic reticulum stress markers were greatly increased in the PCK2 overexpression group, while the marker of tumor malignancy, KI67, was decreased in the PCK2 overexpression group." (PMID 33052225, 2020). "It is also hard to reconcile downregulated PCK2 and SMAD3 transcript levels in tumors from diabetic patients with more vigorous tumor propagation seen in T2DM as PCK2 and SMAD3 have been shown to foster tumor growth and dissemination." (PMID 32971867, 2020). "Our data suggest PCK2 promotes tumor initiation by lowering acetyl-CoA level through reducing the mitochondrial tricarboxylic acid (TCA) cycle." (PMID 29137367, 2017). "Our data suggest that PCK2 promotes tumor initiation through lowering acetyl-CoA level by shunting anion OAA as PEP from mitochondria to the cytosol and thereby reducing the TCA cycle." (PMID 29137367, 2017). "The co-expression of PCK2 with dendritic cell markers, such as CD11C, along with the co-expression of the immune checkpoint PD-L1, implies a potential association between PCK2 and tumor associated DCs mediated immunosuppression." (PMID 39744481, 2025). "Strategies targeting PCK2 could potentially enhance dendritic cell-based immunotherapies, thus restoring and augmenting anti-tumor immune responses." (PMID 39744481, 2025). "For example, studies have revealed that tumor-repopulating cells rely on PCK2-mediated phospholipid remodeling to resist ferroptosis, while CSCs promote PCK2 ubiquitination and degradation through the STAT3/HERC6 pathway, maintaining membrane phospholipids in a ferroptosis-resistant state." (PMID 40932861, 2025). "We also assessed PCK2 mRNA and protein levels in tumor samples isolated from human NSCLC patients." (PMID 39193344, 2024). "Consistently, we found that the ubiquitination level of PCK2 was increased in TRCs compared to bulk tumor cells and could be reversed under Stattic treatment." (PMID 38720107, 2024). "We found that tumor volumes and weights of both A549-shPCK2 and H1975-shPCK2 were significantly decreased compared to those of control cells, indicating the critical role of PCK2 in the growth of NSCLC cells in vivo." (PMID 39193344, 2024). "Finally, glyconeogenesis from Gln has also been reported to occur via PCK2 in some tumor cells and neutrophils and via PCK1 in murine memory CD8+ T cells." (PMID 39424955, 2024). "Additionally, to identify specific tumor types that can be effectively treated by targeting PCK2, it is imperative to develop the biomarkers to predict the response of tumor cells against PCK2 inhibitors." (PMID 39193344, 2024).
tumor (continued). "Moreover, there were less Ki67-positive cells within tumor tissue upon PCK2 knocking down, suggesting a reduced proliferative capacity of these cells." (PMID 39193344, 2024). "Given the role of PEPCK (PCK1 or PCK2) in regulating antioxidants in tumor cells, we investigated whether IGF2BP3lac influences redox homeostasis by modulating PCK2 expression." (PMID 39450426, 2024). "Within the glucose-deprived TME, PCK2 exerts crucial effects to fuel tumor growth." (PMID 37250903, 2023). "KAT8-mediated PCK2 acetylation at K491 impairs lysosomal degradation to elevate PCK2 expression in sorafenib-resistant liver tumor cells, while PCK2 silencing in sorafenib-resistant cells could reduce tumor resistance." (PMID 37250903, 2023). "Moreover, PCK2 expression was necessary for the maintenance of tumor cell proliferation in vitro under glucose-limiting circumstances and for tumor growth in vivo." (PMID 35982907, 2022). "The relevance of these findings for tumor biology is highlighted by an initial analysis of the expression of PCK2 in tumors from the GDC Pan-Can dataset showing increased expression of the gene in tumors presenting missense variant mutations as compared to non-variant samples." (PMID 33413684, 2021). "Therefore, we designed null mutants (PCK2 CRISPR/Cas9 KO) to further investigate the capacity of PEPCK-M to sustain tumor growth in vivo in a xenograft model." (PMID 33413684, 2021). "Inhibition of the responsible enzymes, PCK1 or PCK2, thus might interfere with adaptation and suppress tumor growth." (PMID 33540663, 2021). "Based on the finding that PCK2 inhibits tumor progression by activating endoplasmic reticulum stress in RCC cells, we used immunohistochemistry (IHC) and western blot to assess the level of endoplasmic reticulum stress in vivo and to evaluate the malignancy of the subcutaneous tumors formed." (PMID 33052225, 2020). "Since the tumor center has been shown to be more hypoxic than the tumor margin, central hypoxia might contribute to the decrease in PCK2 expression in this compartment." (PMID 32777161, 2020). "The metabolic tumor microenvironment and the 3‐dimensional context play an important role in modulating both pathways, since PCK2 expression preferentially occurred at the tumor margin and hypoxia regulated both, glycolysis and gluconeogenesis, in NSCLC cells in vitro, albeit in opposite directions." (PMID 32777161, 2020). "PCK2 decreased with increasing tumor size, especially in the LUAD subtype." (PMID 32777161, 2020). "PCK2 expression is important in maintaining the tumor cells in vitro under limited glucose conditions and metabolic enzymes are necessary for proliferation and tumor growth in vivo." (PMID 32699530, 2020). "Based on the stimulatory effect of PURα on EMT and the important role played by PCK2 in tumor metabolism, PURα and PCK2 may represent new therapeutic targets for ESCC." (PMID 33142842, 2020). "It suggests that PCK2 might contribute to dendritic cell infiltration and phenotypic change, possibly inhibiting the initiation and progression of immune responses against the tumor." (PMID 39744481, 2025). "Enrichment of PCK2 in tumors expressing epithelial markers, and its negative impact on distant metastasis-free survival on an epithelial filtered dataset described here puts weight on the later hypothesis as PEPCK-M activity would favor tumor cell survival while inhibiting entosis." (PMID 36002449, 2022). "Thus, the presence of hypoxia could not only be responsible for the lower expression of PCK2 in the tumor center and in larger tumors, but also for the observed histology‐related differences." (PMID 32777161, 2020). "Thus, tumor-type specific differences in the expression/activation of either PCK1 or PCK2 might exist." (PMID 26682254, 2015). "The results showed that compared to the tumor center region, higher expressions of PCK2, CD11C, and PDL1 were detected in the tumor-infiltrated area." (PMID 39744481, 2025).
tumor (continued). "In tumor cells, lactate accumulation induces IGF2BP3 lactylation and enhances m6A methylation of PCK2 and NRF2 mRNAs, reprogramming serine metabolism." (PMID 40165895, 2025). "BHLHE40 has been reported to have tumor suppressive functions and has been shown to affect energy metabolism by regulating PGC-1α, SREBP-1c, PKLR, PCK2, FASN, and PPARγ." (PMID 38301894, 2024). "GPI1, TPI1, GAPDH, PGK1, and PKM2 were consistently upregulated in almost all tumor types, while PCK1, PCK2, and FBP1 were downregulated in tumors." (PMID 35246510, 2022). "In tumor cells of various origins, PCK1 or PCK2 have been found to mediate abbreviated gluconeogenesis, especially under conditions of glucose deprivation, thus contributing to anabolic metabolism." (PMID 32777161, 2020). "In LUAD, the majority of samples (180; 69%) was positively stained for the gluconeogenic enzyme PCK2, while in the LUSC cohort only 38 (40%) of tumor specimens were PCK2 positive." (PMID 32777161, 2020). "Intriguingly, PCK2 is preferentially expressed in the mesenchymal GBM, accompanied by a positive correlation with immune cell infiltration, underscores its potential involvement in shaping the immune landscape within the tumor microenvironment." (PMID 39744481, 2025). "Moreover, the levels of PCK2 and p-ACSL4(T679) were downregulated in TRCs compared to bulk tumor cells in multiple cell lines as well." (PMID 38720107, 2024). "The present study demonstrates that upregulation of PCK2 enhances aerobic glycolysis to promote NE trans-differentiation, in addition to its previously reported function in inhibition of the TCA cycle to promote tumor initiation." (PMID 39014441, 2024). "Importantly, silencing PCK2 increases apoptosis of NSCLC cells under low glucose condition and inhibits tumor growth both in vitro and in vivo." (PMID 39193344, 2024). "It was reported that the expression of gluconeogenic enzymes PCK1, PCK2, and FBP1 predominantly decreased in HCC, and their forced expression induced apoptosis under glucose deprivation conditions, demonstrating the anti-tumor effects of gluconeogenesis in HCC." (PMID 36092708, 2022). "Therefore, PCK2 can serve as a new target for RCC treatment, since it can increase the level of tumor endoplasmic reticulum stress to inhibit tumor progression." (PMID 33052225, 2020). "When we analyzed the abundance of gluconeogenesis and/or glycolysis markers in sections of complete tumors we found an unexpected upregulation of PCK2 at the tumor margins, compared to tumor centers, while for GLUT1 no preference was found." (PMID 32777161, 2020). "In line with observations made by visual inspection, a clearly stronger PCK2 staining was found in the tumor margin, as opposed to the tumor center (P = 0.0012)." (PMID 32777161, 2020). "Restoration of PCK2 expression could activate endoplasmic reticulum stress in RCC, thereby inhibiting tumor progression and increasing tumor sensitivity to sunitinib." (PMID 33052225, 2020). "Interestingly, ER-stress up-regulates ATF4-dependent transcription of mitochondrial PEPCK (PEPCK-M; PCK2), an isoform of PEPCK commonly found in tumor cells." (PMID 31861674, 2019). "However, in the presence or absence of STAT3 knockdown, no significant change was observed in PCK2 mRNA level between TRCs and bulk tumor cells, indicating that STAT3 did not regulate PCK2 through transcriptional level." (PMID 38720107, 2024). "Furthermore, NGS analysis revealed that NF-κB/RELA targets including CCL2, CXCL8, EDN1, IL-1β, IL-6, and SERPINE1 were further reduced and several potential tumor suppressors, such as FABP3, FADS2, FDFT1, SEMA6A, and PCK2, were synergistically induced by the Gefitinib-+IKK16 treatment." (PMID 36358633, 2022).
tumor (continued). "Furthermore, the switch from OXPHOS to glycolysis has also been observed in tumor-repopulating cells (TRCs), a stem cell-like subpopulation with highly invasive phenotypes that are responsible for tumor regeneration, by regulating phosphoenolpyruvate carboxykinase 1 (PCK1) and PCK2." (PMID 40617808, 2025). "Thus, targeting SUCLG1, PCK2, GLDC protein may be a useful strategy to inhibit tumor progression." (PMID 32699530, 2020). "The expression of PCK2 exhibits a strong positive correlation with dendritic cells, while demonstrating a negative correlation with CD8 T cells and tumor purity." (PMID 39744481, 2025). "PEPCK and PCK2 enabled phosphoenolpyruvate conversion from non-carbohydrate substrates to support tumour growth." (PMID 30380689, 2018).
infection (23 papers, 2012 to 2026). The state of being infected such as from the introduction of a foreign agent such as serum, vaccine, antigenic substance or organism. "In contrast, Mkh1/Bck1, Pek1/Mkk2 and two additional orthologues within the CWI pathway (Pck2/PckA (MMYC01_203944) and Pmk1/MpkA (MMYC01_205938)), as well as MMYCO_202020, MMYC01_202201 and MMYC01_201890, are expressed during infection in G. mellonella." (PMID 40906790, 2025). "The expression of pathway genes (TIRB3, ADM2, PCK2) that bind to ubiquitin-like protein ligase and transcriptional corepressor activity were significantly down-regulated after infection by C. perfringens, and significantly up-regulated after 2′-FL treatment." (PMID 35458130, 2022). "Similar to H19 overexpression though, silencing H19 expression also up‐regulated most of the genes involved in lipid breakdown, such as Acat2, Cpt1b, Ndafs4, Pck2, Cyp1a2, Acads and Atpsa1, at 72 hours after Ad‐H19 infection, although most of them were down‐regulated at 36 hours after infection." (PMID 31809000, 2020). "Furthermore, gene expression analysis showed a significant upregulation of key gluconeogenic enzymes, including glucose-6-phosphatase catalytic (G6Pc1) and phosphoenolpyruvate carboxykinase (PCK2), in SFTSV-infected Huh7 cells at 48 hours post-infection (hpi) compared to mock controls." (PMID 40391966, 2025).
kidney disease (3 papers, 2008 to 2025). "There were 7 proteins that exclusively associated only with the kidney domain supporting their proximal role in kidney disease (e.g., A4GALT, PCK2, EFNA3, BTN3A2, IDI2, GATM, FAIM)." (PMID 41282674, 2025).
adenocarcinoma (1 paper, 2026). A common cancer characterized by the presence of malignant glandular cells. "PCK2 and SLC38A2 were highly expressed in human adenocarcinomas tissues." (PMID 41769368, 2026).
cardiovascular disease (1 paper, 2024). "Several proteins linked to increased risk of cardiovascular disease were upregulated in male iVSMCS (PCK2, CD109, and IGFBP2)." (PMID 39796045, 2024).
heart disease (1 paper, 2023). "Pck2 is upregulated in Taz-KD hearts (Pck2, log2(FC) = 1.96; p < 0.0001), which is typical for heart disease." (PMID 37930434, 2023).
PCK2 also shares sentences with these, for which no sentence is quoted: Hepatic steatosis (13 papers); metabolic disease (8); metabolic syndrome (8); hyperlipidemia (3); Impaired glucose tolerance (3); Non-Alcoholic Fatty Liver Disease (3); Cachexia (2); clear cell renal cell carcinoma (2); cyst (2); hepatic (2); ischemia (2); kidney damage (2); lipid metabolic disorders (2); lipodystrophy (2); liver (2); rectal cancer (2); Renal cyst (2); type 1 diabetic (2); Acidosis (1); acute liver failure (1); acute porphyria (1); Alport syndrome (1); anisakiasis (1); Cerebral ischemia (1); cervical squamous cell carcinoma (1); Cirrhosis (1); colon adenocarcinoma (1); Down syndrome (1); epilepsy (1); esophageal carcinoma (1).
A further 36 diseases each share a sentence with PCK2 in 1 paper.